ZNF311 (zinc finger protein 311)
Description:
May be involved in transcriptional regulation.
Synonyms: zf31
Tractability: PROTAC: ubiquitination databases record sites on it.
Gene: Protein-coding gene on chromosome 6 (28,994,040 to 29,005,648, reverse strand). Ensembl gene ENSG00000197935.
Subcellular location: Nucleus
Pathways (Reactome):
Gene expression (Transcription): Generic Transcription Pathway
Gene Ontology:
Molecular function: DNA-binding transcription factor activity, RNA polymerase II-specific; RNA polymerase II cis-regulatory region sequence-specific DNA binding
Biological process: regulation of transcription by RNA polymerase II; regulation of DNA-templated transcription
Cellular component: nucleus
Genetic constraint (gnomAD): Loss-of-function variants: 13 observed, 21.64 expected, observed/expected ratio (o/e) 0.6, 90% interval 0.39 to 0.95. The upper end of that interval is the gene's LOEUF score, 0.95, which puts it in group 4 of 6, group 1 being the genes least tolerant of losing a copy. Missense variants: 727 observed, 829.72 expected, observed/expected ratio (o/e) 0.88, 90% interval 0.82 to 0.93. Synonymous variants: 250 observed, 287.62 expected, observed/expected ratio (o/e) 0.87, 90% interval 0.78 to 0.96.
Homologues: Orthologues: chimpanzee ZNF311 (98% identical), macaque ZNF311 (92% identical), pig ZNF311 (80% identical), rabbit ZNF311 (62% identical), dog ZNF311 (56% identical). Paralogues in human: ZNF708 (43% identical), ZNF568 (42% identical), ZNF595 (42% identical), ZNF726 (42% identical), ZNF728 (41% identical), ZNF724 (41% identical), ZNF429 (41% identical), ZNF254 (41% identical), ZNF33B (41% identical), ZNF484 (41% identical), ZNF85 (41% identical), ZNF658 (40% identical), and 164 more.
Diseases named in the same sentence as ZNF311 in open-access papers:
ZNF311 is named in the same sentence as 8 diseases in open-access papers, as found by Europe PMC text mining. Sharing a sentence is not in itself a finding about the gene and the disease. The quoted sentences say what the papers report.
glioblastoma (1 paper, 2025). The most malignant astrocytic tumor (WHO grade IV). "Additionally, NUTM1 subtype showed subtype-specific expression of ZNF311, which is potentially a novel biomarker for assessing prognosis and immune infiltration in glioblastoma." (PMID 41246237, 2025).
Insulin resistance (1 paper, 2025). Increased resistance towards insulin, that is, diminished effectiveness of insulin in reducing blood glucose levels. "ZNF311 and HCG4 have been previously associated with rheumatoid arthritis and preeclampsia, conditions that are known to be associated with a higher prevalence of insulin resistance compared to the general population." (PMID 40719081, 2025).
tumor (3 papers, 2019 to 2024). "For example, a few zinc-finger genes have been classified as oncodrivers in the Census (e.g., ZNF311) and there is mounting evidence for their involvement in several cancer types, most often as tumor suppressors, by regulating the transcription of genes important for tumor progression." (PMID 31337866, 2019).
cancer (2 papers, 2019 to 2024). A tumor composed of atypical neoplastic, often pleomorphic cells that invade other tissues. "Consequently, we conducted a pan-cancer analysis of gene promoter methylation and observed significant associations between several genes, including ZNF323, ZSCAN23, SCAND3, PRSS16, ZNF391, NKAPL, and ZNF311, and promoter methylation." (PMID 38495498, 2024).
ZNF311 also shares sentences with these, for which no sentence is quoted: glioma (1 paper); preeclampsia (1); rheumatoid arthritis (1); schizophrenia (1).